TNF (tumor necrosis factor)
Diseases named in the same sentence as TNF in open-access papers (continued):
Sharing a sentence is not in itself a finding about the gene and the disease.
hematoma (38 papers, 2013 to 2026). A hematoma is a collection of blood from a vascular structure into an extravascular space. "In recent years, it has been confirmed that the levels of inflammatory factors (such as interleukin-6 and tumor necrosis factor-α) in plasma and dynamic perfusion parameters on MRI are associated with hematoma evolution." (PMID 41137278, 2025). "VEGF levels are significantly increased within hematoma fluid and neomembranes compared with serum samples, and its presence is associated with increased levels of TNF-α and hypoxia-inducible factor-1 α (HIF-1α), both of which are known as VEGF inducers." (PMID 35673314, 2022). "In ICH, TNF alpha has been associated with the size of the perihematoma edema, early hematoma growth which is associated with early neurologic deterioration, poor functional outcome at three months, and increased mortality." (PMID 30613458, 2018). "Results from the two exploratory factor analysis models indicated a different underlying cytokine pattern in venous blood compared with hematoma fluid samples, which seemed especially so for the pro-inflammatory cytokines IL-6 and TNF-α and the anti-inflammatory cytokines IL-4 and IL-13." (PMID 24587250, 2014). "The levels of COX-2, tissue-necrosis factor (TNF-α), and interleukin (IL)-1β in the peri-hematoma tissues were measured." (PMID 38981960, 2025). "The hematoma phase is characterized by the release of pro-inflammatory cytokines such as interleukin-1 (IL-1), tumor necrosis factor alpha (TNF-α), and interleukin-6 (IL-6), which recruit neutrophils and macrophages to the fracture site." (PMID 41008976, 2025). "In SDH rats, vitamin D treatment significantly decreased TNF-α, IL-6, and IL-8 concentrations in the hematoma and meninges." (PMID 41099766, 2025). "Effects of NR on (g) IL-1β and (h) TNF-α mRNA levels in the peri-hematoma tissues 24 h following ICH." (PMID 38981960, 2025). "The expression levels of the three immune factors (IL-1β, IL-6 and TNF-α) in the fracture end hematoma samples were significantly positively correlated with those in the serum samples (P < 0.05)." (PMID 37038178, 2023). "The expression levels of IL-1β, IL-6 and TNF-α in the serum and fracture end hematoma samples of the 48 patients were statistically analyzed, and univariate linear regression analysis was performed." (PMID 37038178, 2023). "The relative expression of IL-1β, IL-6, and TNF-α in the fracture end hematoma samples was positively correlated with the corresponding levels of these immune factors in the serum samples." (PMID 37038178, 2023). "The levels of IL-1β, IL-6 and TNF-α in the serum and fracture end hematoma samples of the two groups were recorded, and their means were compared by independent sample t test." (PMID 37038178, 2023). "Meanwhile, IL-1β and IL-6 returned to basal levels, and the level of TNF-α in the peri-hematoma region was even lower than that in the control group at 7 days post-ICH, indicating a reaction to the continued immune response." (PMID 36792604, 2023). "The serum TNF-α level was positively correlated with the relative expression of TNF-α in the fracture end hematoma samples; the correlation coefficient was 2453.61, and the regression was statistically significant (P < 0.05)." (PMID 37038178, 2023). "The WB results showed that after treatment with UA, the levels of IL-6 and TNF-α in the brain tissues around the hematoma were significantly decreased." (PMID 37834220, 2023). "Laboratory analysis showed that the relative expression levels of IL-1β, IL-6, and TNF-α in the hematoma at the fracture end were 1.0177, 1.0227, and 1.0095, respectively." (PMID 37038178, 2023). "In the present study, elevated admission serum IL-12 levels are closely related to the inflammation (CRP and TNF-α), hematoma volume, and prognosis in ICH patients, substantializing serum IL-12 levels is an inflammation and prognostic biomarker for ICH." (PMID 36303589, 2022).
hematoma (continued). "It has been reported to increase the hematoma volume by inducing inflammation and apoptosis of cerebral VSMCs via the TNF‐α‐dependent nuclear factor‐kappaB pathway." (PMID 34346561, 2021). "We found the evidence that NBP ameliorated neurological deficits, decreased hematoma expansion, brain water content, blood-brain barrier permeability and the expression of pro-inflammatory cytokine TNF-α and MMP-9 when dosed following ICH induction." (PMID 32564011, 2020). "CSDH significantly increases the level of IL-6, IL-8 and TNF-α in the hematoma membrane and its boundary brain tissue on days 3 and 21 after CSDH formation compared to rats subjected to sham surgery." (PMID 31595197, 2019). "Exploratory factor analysis indicated two major underlying immunological processes expressed by the cytokines in both blood and hematoma fluid, but with a different pattern and particularly regarding the cytokines IL-13, IL-6, IL-4 and TNF-α." (PMID 24587250, 2014). "In particular, the cytokines IL-13, IL-6, IL-4 and TNF- α exhibited differences in loadings between an exploratory factor analysis from blood and hematoma samples." (PMID 24587250, 2014). "Similarly, a possible explanation for the correlation between TNF-α levels and SICH patients’ outcomes lies in the finding that patients with early hematoma growth and larger perihematomal hypodensity tend to have higher serum TNF-α levels." (PMID 39970158, 2025). "The blood vessels break, and the formation of a hematoma occurs, which represents a source of hematopoietic cells capable of releasing pro-inflammatory growth factors such as tumor necrosis factor-alpha (TNF-α), bone morphogenetic proteins (BMP), and interleukins (IL-1, IL-6, IL-11, IL-23)." (PMID 39684288, 2024). "The increase in CD36 expression in the perihematomal region is associated with faster hematoma clearance, and reduced CD36 expression increases the production of pro-inflammatory M1 macrophages/microglia mediators, such as TNF-α and IL-1β, thus inhibiting erythrophagocytosis and hematoma clearance." (PMID 35966018, 2022). "In addition, the mRNA levels of IL-1β and TNF-α in brain tissue around hematoma also increased after ICH, which was attenuated by IF." (PMID 35624490, 2022). "Moreover, in comparison with the vehicle group, NBP group showed a lower expanded hematoma volume, brain water content, blood-brain barrier permeability, and TNF-α/ MMP-9 expression level." (PMID 32564011, 2020). "To explore whether NBP has anti-inflammatory effect in ICH rat model, we first examined the expression level of pro-inflammatory factor TNF-α in the brain tissue surrounding the hematoma area." (PMID 32564011, 2020). "We also examined the expression of MMP-9, a downstream of TNF-α in the peri-hematoma cortex tissue." (PMID 32564011, 2020). "In both blood and hematoma fluid, inflammatory cytokines such as tumor necrosis factor (TNF)-α, interleukin (IL)-6 and IL-10 raise, and the anti-inflammatory activities in the hematoma may play a role in the risk of a recurrence of CSDH." (PMID 32328124, 2020). "Compared with the sham group, TNF-α, IL-6, and IL-10 in hematoma increased significantly in the CSDH group (TNF-α: 26.51 ± 5.35 vs 250.31 ± 26.99 pg/ml, P < 0.01; IL-6: 25.76 ± 6.39 vs 112.77 ± 6.91 pg/ml, P < 0.01; IL-10 : 17.60 ± 1.53 vs 82.76 ± 8.12 pg/ml, P < 0.01." (PMID 32328124, 2020). "For example, activated nuclear factor-κB (NF-κB) was seen to migrate into the nucleus at 13–48 h after ICH and at the same time, IL-1β and tumor necrosis factor (TNF) levels increased within 1 day after ICH, while downregulation of TNF-αexpression was associated with reduction in hematoma volume." (PMID 30410928, 2018). "Thus, the effects of TNF-α antagonism on brain water content and hematoma volume were assessed between the groups at 24 hours after injury." (PMID 23962089, 2013).
hematoma (continued). "Levels of serum IL-12 was positively correlated with the admission of NIHSS scores (r = 0.535, P < 0.001), hematoma volume (r = 0.608, P < 0.001), serum CRP levels (r = 0.561, P < 0.001), and serum TNF-α levels (r = 0.533, P < 0.001) in 209 cases ICH patients." (PMID 36303589, 2022). "Our analysis indicated that VEGF, PDGF-BB, TNF-alpha, MMP-9, IL-6, CCL2, IL-1 alpha, MMP-1, MMP-8, and IL-8 were DEGs between the hematoma fluid and the peripheral blood before surgery." (PMID 35207175, 2022). "In addition, our results show that Prdx1 can reduce the hematoma volume after ICH, its mechanism needs further study, we speculate that Prdx1 inhibits the release of inflammatory factors such as TNF-α, thereby promoting the expression of CD36 and causing the absorption of hematomas." (PMID 32210752, 2020). "Since the cytokines IL-13, IL-6, IL-4 and TNF-α in particular displayed a different loading pattern in blood compared to hematoma fluid samples, they could play a different role in the local inflammatory response in the hematoma compared with the systemic response assessed in blood samples." (PMID 24587250, 2014). "Hematoma formation serves as a source of inflammatory cells that release growth factors and pro-inflammatory cytokines, including BMP, interleukins (IL-1, IL-6, IL-11, and IL-23), and tumor necrosis factor-alpha (TNF-α)." (PMID 39907403, 2025). "Furthermore, the knockdown of Nr4a1 significantly increased the expression of p-NF-κB p65, IL-1β, TNF-α, and MMP-9 with a decrease of ZO-1, occludin, and Lama5 in the peri-hematoma tissue." (PMID 31660977, 2019).
herpes simplex infection (38 papers, 2016 to 2024). "KEGG pathway analysis indicated these genes were associated with TNF signaling pathway, NF-kappa B signaling pathway, Toll-like receptor signaling pathway, and Herpes simplex infection." (PMID 35855852, 2022). "In the persistent infection group, the upregulated differential mRNAs were mostly enriched in the NOD‐like receptor signalling pathway, herpes simplex infection, the TNF signalling pathway and the RIG‐I‐like receptor signalling pathway." (PMID 34859581, 2022). "KEGG analysis showed that the enriched pathways were mainly involved in “TNF signaling pathway,” “Influenza A,” and “Herpes Simplex infection”." (PMID 32232013, 2020). "The result showed that these mRNAs were participated in the TLRs signaling pathway, Herpes simplex infection, NLRs signaling pathway, TNF signaling pathway, and NF-κB signaling pathway primarily." (PMID 31684870, 2019). "KEGG pathway enrichment analysis indicates that the differentially expressed genes (DEG) tended to be involved in herpes simplex infection, ribosome and antigen processing and presentation as well as TNF signaling and Toll-like receptor signaling pathways." (PMID 30717799, 2019). "Pathway analysis results showed that DEGs mainly involved in Herpes simplex infection, NF-kappa B signaling pathway, TNF signaling pathway, Toll-like receptor signaling pathway, and NOD-like receptor signaling pathway." (PMID 31309106, 2019). "Our results also suggested that DEGs were mainly enriched in the following pathways: Herpes simplex infection, NF-kappa B signaling pathway, TNF signaling pathway, Toll-like receptor signaling pathway, and NOD-like receptor signaling pathway." (PMID 31309106, 2019). "Proteins related to infection and inflammatory pathways (e.g., Herpes simplex infection, TNF signaling, and Toll-like receptor signaling) were found to be unique to Httex1 72Q, whereas proteins related to metabolism were specifically enriched for Httex1 72Q-GFP." (PMID 34772920, 2021). "KEGG signaling pathway enrichment analysis showed that LFT mainly exerts synergistic anti-inflammatory effects via TNF signaling pathway, herpes simplex infection, RIG-I-like receptor signaling pathway, Toll-like receptor signaling pathway, pathways in cancer, MAPK signaling pathway." (PMID 32276586, 2020). "In the KEGG pathway enrichment analysis, both of these two datasets were mainly enriched in cytokine–cytokine receptor interaction, TNF signaling pathway, chemokine signaling pathway, influenza A, osteoclast differentiation, herpes simplex infection and Toll-like receptor signaling pathway." (PMID 33330617, 2020). "KEGG pathway enrichment analysis showed that the TNF signaling pathway, JAK-STAT signaling pathway, cytokine-cytokine receptor interaction, and herpes simplex infection were downregulated." (PMID 34863175, 2021).
herpesvirus infection (38 papers, 2015 to 2025). "KEGG analysis revealed that the pathways associated with the DEPs included Kaposi’s sarcoma-associated herpesvirus infection, fat digestion and absorption, and the TNF signaling pathway." (PMID 41574377, 2025). "Recently, the World Health Organization Pharmacovigilance Center published the global risk of bacterial skin and Herpesviridae infections with ustekinumab, secukinumab, and TNF-α inhibitors." (PMID 37764964, 2023). "KEGG pathway analysis shows that enrichment in the cytokine–cytokine receptor interaction, TNF signaling pathway, and Kaposi sarcoma-associated herpesvirus infection." (PMID 34870709, 2021). "Several signaling pathways were identified as associated with these DEGs, including human papillomavirus infection, TNF signaling pathway, and Kaposi sarcoma-associated herpesvirus infection." (PMID 34539736, 2021). "Moreover, enrichment in KEGG pathways of Kaposi sarcoma-associated herpesvirus infection, natural killer cell-mediated cytotoxicity and TNF signaling pathways was also observed." (PMID 34465850, 2021). "One possible mechanism involves the uncontrolled release of proinflammatory cytokines (e.g., IL-1β and TNF-α) in response to herpesvirus infection, supporting the proliferation of periodontopathogens and resulting in tissue destruction." (PMID 38251365, 2024). "In detail, the up-regulated genes associated with PCAT-1 overexpression in MM cells were involved in Kaposi's sarcoma-associated herpesvirus infection, MAPK signaling pathway, TNF signaling pathway, Neurotrophin signaling pathway, etc." (PMID 31777580, 2019). "The pro-inflammatory cytokine TNF-α is the main cause of death in an animal model of herpes infection, and a TNF-α antibody reduce death in mice lacking CXCL10." (PMID 39338520, 2024). "“Transferon Oral” modulates IFN-γ, TNF-α, and IL-6 and increases the survival rate in a herpes infection murine model when oropharyngeally (ORO) administered, which correlate with clinical observations where “Transferon Oral” is used as a therapeutic auxiliary in inflammatory diseases." (PMID 33117165, 2020). "Taken together with the findings we report this evidence suggests that treatment of ubiquitous, asymptomatic herpesvirus infections or targeting their downstream counterparts (e.g., TNF-α) could potentially impact the BD-I illness." (PMID 26075105, 2015). "We detected that IFN-α and TNF- α expression was increased significantly in young mice after herpes infection, whereas there was no change in adult and aged mice indicating reduced response to infection with age." (PMID 40732672, 2025).
hypercoagulability (38 papers, 2012 to 2025). "Of interest, TNF-α has been proposed as a risk determinant for VTE in a sub-study of the Leiden Thrombophilia Study, based on the demonstration that individuals with detectable plasma TNF-α levels had a 2-fold increased VTE risk." (PMID 30650562, 2019). "Another possibility is that hypercoagulability caused by augmented TNFα contributes to hepatotoxicity development." (PMID 29317674, 2018). "Interestingely, we also found a strong correlation between the levels of circulating TF and TNFα, that indicates an association between inflammatory responses and hypercoagulability in these patients." (PMID 23311309, 2013). "In addition, the alterations of the EPL thermograms correlate with the prevalence of the polymorphism in PAI-1 genes of thrombophilia and the increased levels of TNF-α and IL-6 established in the blood." (PMID 35955896, 2022). "Furthermore, it has been shown that HSA is associated with markers of systemic inflammation and hypercoagulation (interleukin 6, tumor necrosis factor α, С-reactive protein, fibrinogen, and D-dimer)." (PMID 31703357, 2019). "Also, hypothermia has been observed in mice that have been primed with gram-positive Propionibacterium acnes and challenged with LPS or TNFα, and this response is linked to signs of hypercoagulation and SIRS." (PMID 22792226, 2012). "Additionally, an association between high TNF-α levels and hypercoagulation has also been detected." (PMID 24891849, 2014). "Numerous studies have noted the superior safety profile of transdermal estrogen compared with oral, likely due to upregulation of proinflammatory cytokines IL-1, IL-6, IL-8, and TNF-alpha, which lead to increased thrombophilia when taken orally." (PMID 39659823, 2025). "Elevated fibrinogen, factor VIII, and von Willebrand factor levels promote a hypercoagulable state, while cytokines like IL-6 and TNF-α drive persistent inflammation." (PMID 41181439, 2025). "In patients with COPD, hypercoagulability is primarily driven by chronic hypoxia and inflammatory factors (including IL-6 and TNF-α)." (PMID 40421211, 2025). "TNF-α levels were also significantly higher in the thrombophilia group (10.5 pg/mL, SD: 2.0) compared to the control group (8.9 pg/mL, SD: 1.5), with a p-value of 0.012." (PMID 38533322, 2024). "Second, the increased IL-6 and TNF-α levels in the thrombophilia group point to a potential role for immunomodulatory interventions in treating these patients' repeated pregnancy losses." (PMID 38533322, 2024). "Interleukin-6 (IL-6) and tumor necrosis factor-alpha (TNF-α) levels were higher in the study's thrombophilia group compared to the control group (p=0.029 and p=0.012, respectively), which is another important finding." (PMID 38533322, 2024). "Some proinflammatory cytokines, such as TNF-α, IL-1 and IL-6, can promote the expression of procoagulant molecules and inhibit the expression of anticoagulant molecules, eventually leading to hypercoagulability." (PMID 34319903, 2021). "In a pathophysiological perspective, severe SARS-CoV-2 infection is characterized by numerous dependent pathways triggered by hypercytokinemia, especially IL-6 and TNF-alpha, leading to systemic inflammation, hypercoagulability, and multiple organ dysfunction." (PMID 34057983, 2021). "The connection between RA and VTE is said to be poorly understood, but it is thought that in patients with RA, systemic inflammation and production of cytokines such as tumor necrosis factor-α and interleukin 1 precipitate a state of hypercoagulability." (PMID 32703278, 2020). "According to the results, the PPP samples with the added C3 and TNF-α showed that more parameters point towards hypercoagulation, thus suggesting these molecules have a more profound effect on fibrin formation." (PMID 29379088, 2018). "A significant positive correlation between D-Dimer and TNF-α observed in the present study reinforces the link between inflammation and hypercoagulability." (PMID 26770985, 2016).
hypercoagulability (continued). "Moreover, high-DII diets increase the production of pro-inflammatory cytokines, such as interleukin-6 and tumor necrosis factor-alpha, which trigger vascular inflammation and promote hypercoagulability." (PMID 40686813, 2025). "In order to quantify the extent of the inflammatory process, we determined the levels of proinflammatory cytokines—TNF-α and IL-6 in the blood plasma of the studied groups of women as well as the carriage of 675 4G/4G polymorphism in the PAI-1 thrombophilia gene." (PMID 35955896, 2022). "It is also important to note that TNF-α blockers block the escape of autoimmune B-cells, causing further upregulation of anticardiolipin antibodies, which inhibits the anticoagulant effects of protein C, protein S, and antithrombin III produced downstream of them and promotes hypercoagulability." (PMID 40351429, 2025).